FAP (fibroblast activation protein alpha)
Diseases named in the same sentence as FAP in open-access papers (continued):
Sharing a sentence is not in itself a finding about the gene and the disease.
tumor (continued). "Diverse quinoline‐based FAP inhibitor (FAPI) tracers have recently been developed for positron emission tomography (PET)/computed tomography (CT) imaging, and radiolabeled FAPI tracers have been used in PET imaging for tumor diagnosis." (PMID 40384987, 2025). "In contrast, FAP-expressing tumors were easily resolved using either [89Zr]Zr-H15-Fc or [89Zr]Zr-NGS2405-Fc, as both probes displayed significantly higher localization to tumor sites compared to all other organs within 24 hours." (PMID 39868181, 2025). "In this context, FAPα emerges as a particularly promising target due to its predominant expression in the tumor stroma as opposed to normal tissues, which minimizes the occurrence of adverse effects." (PMID 40918451, 2025). "Additionally, adenoviral vaccines targeting FAP have selectively eliminated CAFs by activating a CD8+ T cell response, thereby reducing tumor growth and metastasis in various murine cancer models." (PMID 40313969, 2025). "Interestingly, G1/S-specific cyclin-E1, and prolyl endopeptidase FAP were unique in ARMS, denoting its crucial role in cell cycle progression and tumor invasion." (PMID 40710368, 2025). "The presence of FAP+ CAFs and DAB2+ TAMs at the tumor boundary may lead to a worse prognosis and poor response to immunotherapy in HCC." (PMID 40051497, 2025). "Moreover, therapeutic drugs can also be delivered by certain nanomaterial delivery systems specifically to CAFs via FAP antibody-drug conjugate (e.g., FAP-targeted liposomes, anti-FAP-PE38 immunotoxin), resulting in potent anti-tumor effects." (PMID 40296919, 2025). "The tumor of U87MG model mice was cut and soaked in formalin solution, and the staining pattern of FAP was obtained after the immunohistochemical staining experiment, which confirmed that all animal experiments of this tracer were carried out in animal models with the FAP expression." (PMID 40006089, 2025). "The pretargeting strategy was subsequently tested in a pancreatic ductal adenocarcinoma patient-derived xenograft model, which better mimics tumor heterogeneity and stromal structure compared to U87MG xenografts, but exhibits significantly lower FAP expression." (PMID 40131608, 2025). "In the absence of a tumor, FAPα exhibits enzymatic functions, including dipeptidyl peptidase and endopeptidase activities, contributing to glucose homeostasis, adipocyte metabolism, and potentially T-cell activation." (PMID 40918451, 2025). "Patients exhibiting high levels of both FAP+ fibroblasts and SPP1+ macrophages demonstrated the shortest progression-free survival period, suggesting the potential synergistic effects of these cell types in promoting tumor progression." (PMID 40191203, 2025). "These lipid-enriched CAFs, characterized by co-expression of ATP-binding cassette subfamily A member 8 (ABCA8) and fibroblast activation protein (FAP) (ABCA8+FAP+), promote tumor metabolism through ABCA8-mediated lipid transfer to fuel mitochondrial oxidative phosphorylation (OXPHOS)." (PMID 40861469, 2025). "Given that FAP IHC expression was analyzed as a binary variable (positive vs. negative), tumor size—a continuous variable—was transformed into categorical groups to enable statistical comparison using the chi-square test." (PMID 41303595, 2025). "A novel FAP-based method, molecular pro-theranostic probe (FMP) with activatable fluorescence, photoacoustic (PA) imaging, and photodynamic therapy (PDT), is able to completely repress primary tumor." (PMID 40248695, 2025). "Still, FAP expression varies by CAF subtype and tumor stage." (PMID 41441395, 2025). "In tumor tissue, the combination of FAP-IL2v and pembrolizumab did not induce consistent on-treatment changes in key tumor-infiltrating lymphocyte (TIL) populations; a mixed pattern was observed in both schedules." (PMID 39895413, 2025).
tumor (continued). "Collectively, these data suggest that stimulation by FAP antigen substantially increases pro-inflammatory cytokine secretion by FAP/IL-15 CAR-T cells, thus facilitating localized inflammatory responses and efficient tumor targeting." (PMID 41455698, 2025). "The interactions between FAP’s enzymatic and non-enzymatic activities, and the molecular pathways through which sFAP influences tumor progression, require further investigation." (PMID 41373408, 2025). "Although tumor size and weight remained comparable between both groups, immunohistochemical (IHC) analysis revealed a significant increase in α-SMA(+), Collagen I(+), and FAP(+) fibroblasts in MTCQ1-EGFRvIII-derived tumors." (PMID 40472740, 2025). "Nevertheless, the consistent univariate association between FAP expression and both DFS and OS reinforces its relevance as a prognostic marker within the tumor stroma, even if not retained as an independent factor in multivariate modeling." (PMID 41303595, 2025). "It is important to note that targeting FAP to eliminate the tumor stroma does not inherently lead to antitumor effects." (PMID 40656546, 2025). "They screened FAPI-04 with higher affinity to FAP, which demonstrated optimal tumor and non-target tissue distribution in preclinical imaging experiments, showing a longer retention time in tumor compared to FAPI-02." (PMID 40438601, 2025). "While this study focused on [68Ga]Ga-FAPI-04, it is important to acknowledge that other FAP-targeting tracers, such as [68Ga]Ga-FAPI-46 and [18F]F-FAPI-74, may exhibit different pharmacokinetics, tumor retention profiles, and background uptake characteristics." (PMID 41301015, 2025). "These images suggest that the FAP-positive area was located in the tumor nest rather than in the capsule surrounding the tumor nest." (PMID 40126602, 2025). "The subset of FAP+ cells within cluster 6 were considered to denote activated PSMC, which were readily observed in nests at the tumour front and in activated benign-adjacent tissues, particularly adjacent to glands exhibiting PIN, basal cell hyperplasia or corpora amylacea." (PMID 41378308, 2025). "Regarding the CAR-T cell therapies, studies demonstrated FAP CAR-T cells reduced tumor growth in murine models without notable toxicity and weight loss." (PMID 40855046, 2025). "Furthermore, FAP and AMPH were related to stromal infiltration and stemness in most tumors, indicating a key role in tumor occurrence and development." (PMID 40433364, 2025). "Despite completely different targeting strategies, where CEA-IL-2v and FAP-IL-2v target tumors and PD1-IL-2v targets tumor-infiltrated T cells, these IL-2v fusion proteins showed comparable tolerability in humans, with maximal tolerated doses of approximately 0.3-0.5 mg/kg." (PMID 40046051, 2025). "In pancreatic ductal adenocarcinoma (PDAC), CXCL12 produced by FAP+ CAFs coats tumor cells and excludes T cells; CXCR4 blockade (AMD3100) disrupts this barrier, permits intratumoral CD8+ accumulation, and synergizes with anti-PD-L1." (PMID 40940809, 2025). "In contrast, RAC2‐high tumours (MP3‐dominant) showed lacked FAP expression and maintained abundant CD8 T cell infiltration." (PMID 40292733, 2025). "Primary HPB tumours are a promising group of malignancies for FAPI PET imaging, as they are histopathologically characterised by a high stromal content and recruitment of FAP-expressing CAFs." (PMID 40076605, 2025). "While FAP-directed CAR T cells and vaccines effectively eliminated FAP+ CAFs, increased CD8+ T-cell infiltration, and decreased fibrotic stroma, their clinical application was limited by on-target/off-tumor toxicity due to FAP expression in healthy tissues." (PMID 40693266, 2025). "Specificity towards FAP of both compounds was demonstrated by pre-injection of 100 nmol FAPI-04 resulting in an almost complete lack of uptake (> − 90%) in the hFAP-HT1080 tumor for [68Ga]Ga-NODAGA-FAP647." (PMID 41348275, 2025).
tumor (continued). "Anastasia Loktev’s team developed FAP targeting molecules by further optimizing FAPI-04 to increase radio-dose in tumor whereas maintaining low non-specific binding to normal tissues." (PMID 40438601, 2025). "By targeting this FAP-rich microenvironment, [68Ga]Ga-FAPI PET tracers yield exceptionally high tumor-to-background contrast and minimal physiologic uptake, providing superior lesion conspicuity within the musculoskeletal system compared with glucose-based imaging." (PMID 41226078, 2025). "The histological results suggest that in tissues from patients with MIBC, the number of FAP + fibroblasts is significantly greater in the stroma than in the tumor region, whereas the number of α-SMA + fibroblasts is not significantly different." (PMID 40319103, 2025). "The tumour inhibitory potential of FAP inhibitors has been explored but proved not particularly effective." (PMID 41049848, 2025). "Notably, the concurrent reduction in FAP and CD206 expression suggests that Antrocin’s effects on tumor microenvironment modulation, initially observed in vitro, are supported in the more complex tumoroid setting." (PMID 41009348, 2025). "FAP inhibitors (FAPIs) labeled with PET tracers have rapidly advanced as a novel imaging modality with broad clinical applications that offers several advantages, including rapid tumor accumulation, low background uptake, and high tumor-to-background ratios." (PMID 40283957, 2025). "Moreover, nanoparticles can be functionalized with ligands targeting specific tumor or stromal markers, such as epidermal growth factor receptor (EGFR), integrins, or FAP, to further improve targeting specificity." (PMID 41179287, 2025). "FAP-targeting radioligands such as FAP8-IP-DOTA exhibit high affinity and specificity, providing high-contrast tumor microenvironment images and prolonged retention in tumors, suitable for precise tumor localization and repeated treatment." (PMID 39911388, 2025). "FAP-targeting radiopharmaceuticals do not directly target tumor cells but instead target CAFs, the core component of the tumor mesenchyme." (PMID 40438601, 2025). "Statistically significant antitumor activity was observed, with tumor growth inhibition rates of 111% and 113% (p < 0.05) in HEK-FAP tumor-bearing mice treated with 30 or 60 MBq of 177Lu-FAP-2286, respectively, compared to the vehicle-treated group, with no significant weight loss." (PMID 40805245, 2025). "In contrast, FAP-expressing tumors were easily resolved using either [89Zr]Zr-H15-Fc or [89Zr]Zr-NGS2405-Fc, as both probes displayed significantly higher localization to tumor sites compared to all other organs within 24 h." (PMID 40804296, 2025). "Furthermore, the tumor with better efficacy is infiltrated with less fibroblasts, including α-SMA (mean: 0.174 vs 2.412, p = 0.314), FAP (mean: 0.546 vs. 1.677, p = 0.393), FSP (mean:0.695 vs. 4.078, p = 0.201)." (PMID 41225509, 2025). "Fibroblast activation protein α (FAP‐α) interferes with anti‐tumor immunity, as evidenced by a subcutaneous mouse model of PDAC where depletion of FAP‐α induced an immune response and resulted in tumor regression." (PMID 40437741, 2025). "Additionally, an oral DNA vaccine targeting FAP has shown promise in enhancing CD8+ T cell–mediated CAF killing, reducing tumor growth and metastasis in preclinical models." (PMID 40173050, 2025). "Various of factors may influence a tumor’s response to FAP targeting for radiotherapy, including FAP expression in the TME, biological behavior of the tumor, and the interaction between the tumor and surrounding normal tissues." (PMID 40438601, 2025). "In lung adenocarcinoma models, radiotherapy induces tumor cells to release HMGB1, which activates CAFs through the TLR4/PI3K/AKT pathway—driving conversion to the myCAFs phenotype with upregulated FAP, α‐SMA, and Collagen I expression, thereby enhancing tumor fibrosis and invasiveness." (PMID 41354099, 2025).
tumor (continued). "The correlative data between tissue CCA FAP expression, demographic data, and tumor characteristics are based on TMA and not full tissue sections." (PMID 39664608, 2024). "An analysis of 59 NSCLC patient specimens after tumor resection indicated that high expression of FAP is a negative indicator of poor survival." (PMID 39403603, 2024). "It’s worthy of our further investigation on how FAP+ cells orchestrate immune cell function using more desmoplastic, non-immunogenic mouse tumor models and human xenografts." (PMID 39086477, 2024). "Thus, targeting FAP addresses the tumor microenvironment (TME), compared to other tumor targets that generally target the tumor cells directly." (PMID 39335703, 2024). "In this regard, Ohlund and his colleagues reported that CAFs with a low expression level of the α-SMA marker produce a large amount of IL-6, and CAFs that express a high amount of FAP and α-SMA produce more TGF-β that both subtypes play an important role in tumor progression." (PMID 39030445, 2024). "Our study found that ANO1 expression positively correlated with FAP-positive CAFs and negatively correlated with CD8-positive TILs, suggesting that ANO1 may be a key regulator of the tumor immune microenvironment." (PMID 38352864, 2024). "Despite the potential of FAP-targeted radioligands shown in these studies, their tumor retention and efficacy have not been promising in the clinic." (PMID 38398552, 2024). "In this study, the authors examined the combined effect of FAP-IL2v with PD-1 blockade in a Panc02-H7-Fluc tumor model and observed no therapeutic synergy between them." (PMID 39218982, 2024). "Furthermore, the presence of SPP1+ macrophages in the triad structure, alongside endothelial and POSTN+ FAP+ CAFs, suggests a role in promoting tumor development through pro‐angiogenic properties and activation of CD44 in tumor cells." (PMID 39716897, 2024). "The receptor binding properties and tumor targeting were examined both in vitro and in vivo by using NCI-H727 (SSTR2/FAP, positive) and Mc38 (SSTR2/FAP, negative) cell lines and tumor-bearing mouse models." (PMID 39770488, 2024). "This leads to better LNCaP tumor-to-blood contrast ratios for [68Ga]Ga-AV01084 (4.09 ± 0.77) and [68Ga]Ga-AV01088 (4.10 ± 0.88) than our previously reported bispecific PSMA/FAP tracers (0.48–0.89)." (PMID 38398552, 2024). "Studies evaluating the use of a FAP targeting antibody alone to potentially deplete FAP+ cells have had limited to no anti-tumor efficacy in clinical trials." (PMID 39335130, 2024). "Therefore, we assumed that IL-17a stimulation leads to the upregulation of FAP expression, activation of stellate cells, and promotion of the growth and proliferation of HCC cells in the tumor microenvironment." (PMID 38740736, 2024). "In this study, we used anti-mouse fibroblast activation protein (FAP) antibody to target FAP+ CAFs (FAP-targeted NIR-PIT) and investigated whether this therapy could suppress tumor progression and improve tumor immunity." (PMID 38555315, 2024). "FAP is expressed in the stroma of a high proportion (93%) of primary CCA independent of patient clinical or tumor pathology features." (PMID 39664608, 2024). "The overexpression of FAP in pancreatic cancer CAF can remodel ECM through modulating fibronectin levels and increasing the organization of collagen fiber, further forming a hardened and parallel fiber that increases the directionality of tumor cell invasion." (PMID 38644492, 2024). "In vivo SPECT imaging employing 111In-FAP-2286 in HEK-FAP tumor-bearing mice showcased stable accumulation within tumor tissues, accompanied by minimal uptake in non-tumor regions." (PMID 38543239, 2024). "By eliminating fibroblasts with anti-FAP NIR-PIT, we may see a similar phenomenon due to the reduction of CAFs and subsequently increased permeability due to a reduction in tumor pressure." (PMID 38275890, 2024).
tumor (continued). "Notably, FAP expression was observed in both CAF and tumor cells, in contrast to other markers that are predominantly expressed in CAFs." (PMID 38606999, 2024). "The higher amounts of tumor stroma compared to tumor cells could explain the supplementary effect of [68Ga]Ga-FAPI when added to [18F]FDG, since the stroma contain FAP-expressing CAFs." (PMID 37584717, 2024). "Using co‐culture assays, we confirmed FAP‐CAR‐T cells mediate bystander killing of antigen‐negative tumor cells, but only after activation by FAP‐positive target cells." (PMID 38975278, 2024). "MDA-MB-231 was chosen as the TNBC cell line in this study for two key reasons: it is the most commonly utilized cell line and although MDA-MB-231 does not inherently express FAP, it does so when co-cultured with fibroblasts in tumor tissues." (PMID 39519118, 2024). "Similarly, chemotherapy was shown to repress the expression of FAP in CAF in PDAC109, confirming the impact of treatment on CAF-S1 in another tumor type." (PMID 38346978, 2024). "Evidently, overexpression of FAP on the tumor cells does not represent the clinical tumor histopathology of FAP-expressing CAFs, situated next to the cancer cells." (PMID 39718718, 2024). "A FAP+PDPN+ population of CAFs, which are located at the outer edge of the tumour, contributes to inhibiting the proliferation of T cells, while FAP+PDPN− population appear not to be immunosuppressive." (PMID 38158643, 2024). "By targeting FAP+ CAF, CAR-T cells could disrupt tumor’s immunosuppressive niches, ultimately enhancing immunotherapy efficacy." (PMID 38561380, 2024). "In this study, we generated CAR T cells with cytoplasmic domain combinations of 4-1BB instead of CD28 that can target both human FAP (hFAP) and mouse FAP (mFAP), and detected the killing function of FAP-CAR T on FAP+ tumor cells as well as human and murine primary CAFs in vitro and in vivo." (PMID 39086477, 2024). "Furthermore, through correlation analysis, we demonstrated that concentrations of BMP-9, FAP, follistatin, MIA, and VEGF-A significantly (p ranging from 0.041 to 0.0012) correlate with tumor size (measured in cm)." (PMID 39511039, 2024). "Moreover, FAP and EGFR have been shown to enhance T cell activation and accumulation at the tumor site, thereby increasing anti-tumor efficacy." (PMID 39055561, 2024). "The co-citation network of FAP research shows a dichotomy: one group is centered on FAPI tracers, while the other focuses on non-radioactive FAP-targeted therapy and the expression of FAP in the tumor microenvironment." (PMID 39758423, 2024). "Despite multiple studies showing FAP to be involved in tumor progression, the exact role of FAP in the TME is not well understood." (PMID 38540158, 2024). "Another study suggested that FAP expression of the primary tumor was significantly higher in patients who did not benefit from immune checkpoint blockade (ICB) therapy, making FAPI-PET a potential predictor of immunotherapy response." (PMID 40604259, 2024). "However, the tumor uptake values from the bispecific tracers were still lower than those obtained from the monospecific tracers, PSMA-targeted [68Ga]Ga-PSMA-617 and FAP-targeted [68Ga]Ga-AV02070." (PMID 38398552, 2024). "FAP-expressing CAF cells could mediate immunosuppression, as removal of these cells enhanced T cell mediated killing of tumor cells." (PMID 39030445, 2024). "Recently, it has also been reported that FAP-CAR T cells could deplete stromal cells and matrix-dense network surrounding tumor nests, thus disrupted immune exclusion." (PMID 39086477, 2024). "Furthermore, it has been observed that Wnt2B released from exosomes of tumor cells positively regulates α-SMA and FAP expression in vitro and in vivo and these acquire a greater capacity for proliferation and migration." (PMID 38606999, 2024).